AR (androgen receptor)
Diseases named in the same sentence as AR in open-access papers (continued):
Sharing a sentence is not in itself a finding about the gene and the disease.
Kennedy disease (continued). "Spinal and bulbar muscular atrophy (SBMA), also known as Kennedy’s disease, is an X-linked autosomal recessive MND caused by a trinucleotide repeat in the AR gene." (PMID 39596864, 2024). "The expansion of CAG trinucleotide repeats (CAGn > 38) in exon 1 of the AR gene leads to reduced AR signaling and is responsible for Kennedy disease." (PMID 39797240, 2024). "Kennedy's disease (KD), also known as spinal and bulbar muscular atrophy (SBMA), is a rare, X-linked recessive androgen receptor gene mutation affecting approximately one in 40,000 males." (PMID 35228980, 2022). "Spinal and bulbar muscular atrophy or Kennedy disease, a rare X-linked neuromuscular disease caused by a CAG repeat expansion in the first exon of the androgen receptor gene, is manifested by bulbar symptoms, muscle cramps, leg weakness, and tremor." (PMID 34381412, 2021). "Spinal and Bulbar Muscular Atrophy, also known as Kennedy's disease, is an X-linked trinucleotide repeat disorder due to expansion of cytosine-adenine-guanine (CAG) repeat in the androgen receptor gene." (PMID 34484106, 2021). "Men with a mutation in AR(CAG)n (where n refers to the number of CAG repeats, n ​> ​38) manifest Kennedy’s disease or spinobulbar muscular atrophy, while low n alleles have been associated with risk for prostate cancer and benign prostatic hyperplasia." (PMID 32593802, 2020). "The Spinobulbar muscular atrophy [(SBMA) Kennedy's disease] is a X-linked hereditary lower motor neuron disease, where the expanded trinucleotide repeat (CAG > 37) in the androgen receptor gene (AR) causes its nuclear inclusions and impairment of its function." (PMID 30787905, 2019). "Here, we review the role the folding of the AR plays in the pathogenesis of spinal-bulbar muscular atrophy (SBMA), a neuromuscular degenerative disease arising from expansion of the polyglutamine repeat." (PMID 28031874, 2015). "The AR-NTD cloned from the genomic DNA of a patient with Kennedy's disease, with Q45, showed a modest increase in α-helix and decrease in β-structures." (PMID 28031874, 2015). "Expansion of the large polyglutamine repeat in the amino-terminal domain of the AR is responsible for the neuromuscular degenerative disease spinal-bulbar muscular atrophy." (PMID 28031874, 2015). "The CACNA1A calcium channel subunit in SCA6 is primarily expressed in affected cerebellar Purkinje cells, while the AR in Kennedy’s disease is principally expressed in vulnerable motor neurons." (PMID 26331033, 2014). "Spinal and bulbar muscular atrophy (SBMA) or Kennedy's disease is an X-linked CAG/polyglutamine expansion motoneuron disease, in which an elongated polyglutamine tract (polyQ) in the N-terminal androgen receptor (ARpolyQ) confers toxicity to this protein." (PMID 25392924, 2014). "Spinal bulbar muscular atrophy (SBMA), also known as Kennedy's disease, is an X-linked recessive disease caused by a CAG-repeat expansion in the gene coding for the androgen receptor, leading to a poly-Q repeat expansion in the protein." (PMID 24600344, 2014). "For instance, with Kennedy's Disease, a normal individual will have 21 tandem copies of a CAG repeat within an androgen receptor gene, while an individual with Kennedy's Disease will have 40-52 copies of the CAG repeat." (PMID 20515480, 2010). "Androgen receptor function is known to be important for motor neurone survival, and disruption of this function in Kennedy's disease contributes to the motor neurone degeneration seen in this condition." (PMID 20346106, 2010). "We also performed a search in the Scopus database using the keywords "Kennedy disease", "spinal and bulbar muscular atrophy", "AR gene", and "Latin America", limiting the search to the available Latin American countries (Argentina, Brazil, Colombia, Honduras, Mexico, Panama, Peru, and Puerto Rico)." (PMID 40416113, 2025).
Kennedy disease (continued). "Spinal and bulbar muscular atrophy (SBMA), commonly referred to as Kennedy’s disease, is an X-linked recessive disorder resulting from a trinucleotide repeat expansion in the androgen receptor (AR) gene." (PMID 40430041, 2025). "Trinucleotide repeat expansion disorders such as Kennedy’s disease (spinal bulbar muscular atrophy; AR gene CAG expansion) and myotonic dystrophy type 1 (Dystrophia Myotonica Protein Kinase—DMPK gene CTG expansion) are increasingly being recognized as etiologies of subfertility." (PMID 41465244, 2025). "An understanding of the disorders began with the identification of (CGG)n trinucleotide repeats within the 5′ untranslated region (UTR) of FMR1 gene in Fragile X syndrome and (CAG)n trinucleotide repeats within the coding region of the androgen receptor (AR) gene in spinobulbar muscular atrophy." (PMID 38929088, 2024). "Our 49-gene panel was comprehensive for MND-spectrum genes but we did not examine the androgen receptor CAG trinucleotide repeat associated with Kennedy disease, nor did we exhaust all rare HSP and PLS-associated genes." (PMID 36515702, 2023). "Spinal and bulbar muscular atrophy (SBMA), also called Kennedy’s disease, is a neurodegenerative X-linked recessive proteinopathy caused by CAG repeat expansions in exon 1 of the gene encoding the androgen receptor (AR)." (PMID 37759656, 2023). "At the time this sort of mutation was unusual, shared only with another disorder X-linked spinal and bulbar muscular atrophy (SBMA; also known as Kennedy’s disease) whose genetic basis, expansion of a CAG/CTG-repeat tract in the androgen receptor gene, was discovered the same year." (PMID 27657135, 2016). "Spinal and bulbar muscular atrophy (SBMA), also known as Kennedy’s disease, is an X-linked degenerative motor neuron disease caused by a polyglutamine encoding CAG repeat expansion in exon 1 of the androgen receptor gene." (PMID 24898351, 2014). "A sample of individuals with spinal and bulbar muscular atrophy (SBMA or Kennedy disease), an X-linked degenerative neuromuscular disorder caused by a CAG trinucleotide repeat expansion in the first exon of the androgen receptor gene (AR), participated in this study." (PMID 24876969, 2014). "Kennedy disease/spinal bulbar muscular atrophy (KD/SBMA), is a progressive neuromuscular disease, which is caused by an expanded trinucleotide repeat length encoding the polyglutamine (polyQ) tract of the androgen receptor (AR) gene." (PMID 20886071, 2010). "In a transgenic mouse model of spinobulbar muscular atrophy (SBMA), a motor neuron disease caused by misfolded protein aggregation, NtB administration of a PACAP analog reduces Ser96 phosphorylation of the polyglutamine (polyQ) expansion of the androgen receptor." (PMID 37631246, 2023). "However, studies show that loss of AR function alone, as in androgen insensitivity syndrome does not cause the motor neuron degeneration that occurs in Kennedy disease." (PMID 25928806, 2014). "Huntington's disease, spinal and bulbar muscular atrophy, and spinocerebellar ataxia 17 (SCA17) are caused by expansions in the polyglutamine (polyQ) repeats in Huntingtin protein (Htt), androgen receptor protein (AR), and TATA-binding protein (TBP), respectively." (PMID 17868456, 2007). "In five couples with Kennedy disease, there were no informative SNPs in the 5’ flanking region of the AR gene, which is thought to be due to the small number of SNPs in the centromeric region of the X chromosome." (PMID 40710390, 2025). "Patient 22 was the only male with a negative NGS panel and WES, and thus benefited from specific genetic testing for Kennedy disease (AR gene), which was also negative." (PMID 37337091, 2024). "For example, in 2002 Takeyama and co-workers developed a spinobulbar muscular atrophy (SBMA) Drosophila model, consisting of CAG expansion in androgen receptor (AR) gene, and showed that a ligand-dependent activation of AR is necessary for motor neuron degeneration." (PMID 25859781, 2015).
COVID-19 (82 papers, 2020 to 2025). A disease caused by infection with severe acute respiratory syndrome coronavirus 2. "This suggests a potential mechanistic explanation for differential COVID-19 susceptibility and provides a rationale for investigating AR-targeted therapies as potential protective interventions against SARS-CoV-2 infection severity." (PMID 41150771, 2025). "Androgen receptor signaling and its genetic variability have been already linked to COVID-19 severity and its inhibition proposed as a therapeutic strategy (e.g34)." (PMID 36289370, 2022). "Androgen receptor polymorphism—The gender discrepancy in COVID-19 mortality and severity has a multifactorial etiology." (PMID 36101355, 2022). "A shorter length of the CAG trinucleotide repeat in the first exon of AR genes, an alteration that is common in males with this type of disorder, has been linked to more severe and fatal COVID-19 cases." (PMID 35327605, 2022). "Analysis of other variables here also showed that ACE2 and AR levels were elevated in older male smokers, providing a possible link between smoking and age risk factors with a more severe COVID-19 disease course." (PMID 33310900, 2020). "Another possible mechanism underlying the male-female discordance in COVID-19 mortality involves the role of the androgen receptor, the gene for which is located on the X chromosome." (PMID 33117953, 2020). "Moreover, in men with androgenetic alopecia, there is a risk of more severe forms of COVID-19, as explained by a vulnerability mediated by genetic polymorphisms of the androgen receptor." (PMID 37511952, 2023). "Other than the enhanced influence on adaptive immune response after vaccination, anti-androgen therapy could also decrease the susceptibility for COVID-19 among androgen sensitive phenotypes since the androgen receptor shares the same locus with SARS-COV-2." (PMID 36119091, 2022). "The authors hypothesized that the low triplet number is associated with a more active AR, which may mediate the immunosuppressive effects of testosterone, thus counteracting the cytokine storm typical of the severe form of COVID-19." (PMID 36101355, 2022). "Similarly, less favorable outcome in COVID-19 has been associated with poly-glutamic (PolyQ) repeat number of Androgen receptor (AR) and serum testosterone concentration." (PMID 34578250, 2021). "Additionally, AR is associated with COVID-19 comorbidities, and recently implicated in the severity of COVID-19 in women with polycystic ovarian syndrome, a disorder associated with high androgen levels and androgen sensitivity." (PMID 34616619, 2021). "A more recent prospective longitudinal study of hospitalized males with COVID-19 suggested that longer AR CAG repeats are associated with a more severe form of the disease, supporting the active role of testosterone in the pathogenesis of the complicated disease." (PMID 33796068, 2021). "Accordingly, heterogeneity secondary to polymorphisms in the androgen-receptor gene may contribute to the male-female disparities in severe COVID-19 cases." (PMID 33117953, 2020). "Since the expression of ACE2 in the myocardium appears to be modulated by androgen, a role for androgen receptor (AR) gene polymorphisms cannot be excluded in the pathogenesis of cardiovascular adverse events and hypertension in COVID-19-positive male patients." (PMID 32331343, 2020). "We hypothesized that COVID-19 could be a possible trigger for the development of infertility and therefore investigated if an associated increase in miR-371a-3p levels exists, resulting in the downregulation of the AR." (PMID 35453608, 2022). "Given the inverse relationship between the number of triplets and androgen receptor activity, these results could allow us to hypothesize that a longer polymorphic tract increases the risk of developing a severe form of COVID-19 due to a reduction in receptor-mediated immunosuppressive signaling." (PMID 36101355, 2022).
COVID-19 (continued). "Additionally, AR mutations or other gene polymorphisms along the pathway of SARS-CoV-2 pathogenesis may further lead to COVID-19 progression and deterioration." (PMID 34912345, 2021). "Additionally, as in various ethnic backgrounds, AR mutations or other gene polymorphisms along the pathway of SARS-Co-2 pathogenesis may further lead to COVID-19 expansion and deterioration." (PMID 33796068, 2021). "AR-targeting compounds became one of the initial groups of drugs to be pursued as potential COVID-19 treatments for the myriad of reasons discussed in preceding sections." (PMID 37459541, 2023). "Another AR antagonist, proxalutamide, is in ongoing phase 3 studies for COVID-19 after showing initial positive findings." (PMID 37459541, 2023). "As a selective androgen receptor antagonist, flutamide induced a two-fold reduction in ROS activity in neutrophils from male patients with COVID-19." (PMID 37896963, 2023). "Proxalutamide, an AR antagonist, was shown in initial clinical studies to benefit COVID-19 patients; however, further validation is needed as one study was retracted." (PMID 37459541, 2023). "This trial study on androgen receptor antagonists which is a novel therapeutic target in COVID-19, inhibiting SARS-CoV-2 infection by regulating ACE2 and TMPRSS2." (PMID 37322522, 2023). "Several studies explored the mechanism of TMPRSS2 regulation by AR and the possible applications for treating COVID-19." (PMID 36834705, 2023). "The comparison of a 6-gene signature (ACE2, TMPRSS2, AR, TLR7, IL6, and IRF5) was made to explore the sex-based differences associated with COVID-19." (PMID 36992366, 2023). "An American first author conducted a Brazilian study to describe if Proxalutamide (PubChem CID: #60194102; C24H19F4N5O2S), an androgen receptor antagonist, was effective in treating men with COVID-19 in an outpatient setting." (PMID 36767202, 2023). "Proxalutamide as an androgen receptor antagonist has shown potential treatment effects on COVID-19 patients." (PMID 37322522, 2023). "In COVID-19 samples where the AR levels were reduced, the miR-371a-3p was significantly upregulated." (PMID 35453608, 2022). "Why should COVID-19 reduce AR which is necessary for the production of the docking and internalization receptors (TMPRSS2 and ACE2)?" (PMID 35453608, 2022). "As such, discordant efficacy between luteinizing hormone releasing hormone antagonists and AR antagonists for COVID-19 is conceivable." (PMID 35438754, 2022). "Recently, androgen receptor CAG repeat length has been found to predict COVID-19 severity indicating the importance of genetically determined AR sensitivity in the mediation of androgen impact on COVID-19 outcome in men." (PMID 35602518, 2022). "Hypersensitivity of the androgen receptor (AR) revealed through the AR gene was demonstrated to be a determinant of COVID-19 prognosis." (PMID 34976549, 2021). "Taken together, there is sufficient evidence to explore more about the use of drugs that reduce androgen receptor as a promising therapeutic option against COVID-19." (PMID 33643746, 2021). "The increased case incidence and disease progression severity from COVID-19 observed in men can be, at least partially, explained by increased androgen levels and/or AR activation." (PMID 34575910, 2021). "What is the relation between testosterone levels, androgen receptor mutations/polymorphisms and TMPRSSE2 function in priming SARS-CoV-2 spike proteins, and in turn COVID-19 morbidity and mortality?" (PMID 33796068, 2021). "Collectively, in both males and females, not only hyperexpression and hyperactivity of androgens are possibly a major predictor of COVID-19, but AR suppression can reduce the severity of COVID-19." (PMID 34976549, 2021). "An androgen receptor signaling inhibitor proxalutamide was also investigated in 3 RCTs for its effectiveness in treating COVID-19." (PMID 34391321, 2021).
COVID-19 (continued). "There is a current controversy concerning the usage of ACE inhibitors and AR blockers in patients with COVID-19." (PMID 34554559, 2021). "Collectively, our study highlights the strong need for effective, selective, and safe androgen receptor blockers to mitigate not only metabolic and cardiovascular symptoms in women with PCOS but also possible COVID-19-associated outcomes." (PMID 34575910, 2021). "There are currently several clinical trials actively assessing the effectiveness of targeting AR in treating COVID-19 patients using new or re-purposed anti-androgens." (PMID 34328182, 2021). "Among these, AR and 5alpha-reductase inhibitors deserve attention, since they provide prompter anti-androgenic actions and some present additional anti-COVID-19 properties." (PMID 32993622, 2020). "Second, our findings provide a rationale for investigating AR antagonists as an adjunctive therapy in high-risk non-cancer patients with COVID-19, particularly males with elevated androgen levels." (PMID 41150771, 2025). "Additionally, androgen receptors (AR) are involved in the severe outcome of viral infections such as COVID-19 and hepatitis B virus (HBV)." (PMID 36992366, 2023). "Thus, androgen plays a crucial role in SARS-CoV-2 infection and the androgen receptor (AR) blockers would likely improve the treatment effect of COVID-19." (PMID 37322522, 2023). "Notably, proxalutamide, an antagonist of AR, underwent clinical trials for its effectiveness in treating COVID-19 and received an EUA in Paraguay for treating hospitalized COVID-19 patients." (PMID 37936830, 2023). "In conclusion, we found a high rate of COVID-19 vaccination among uro-oncology patients receiving systemic targeted therapy with tyrosine kinase receptor inhibitors (TKIs) for mRCC and systemic therapy with androgen receptor target agents (ARTAs) for mCRPC." (PMID 37243015, 2023). "These preliminary observations prompted a burst of basic science and clinical studies to attempt to elucidate the role of androgens in SARS-CoV-2 infection and determine whether AR inhibitors could be viable treatment options for COVID-19." (PMID 37459541, 2023). "This link could pave the path to novel strategies, including re-purposing approved androgen synthesis inhibitors or androgen receptor antagonists to treat COVID-19." (PMID 35625699, 2022). "Interestingly, a study by McCoy et al10 reported results of a clinical trial testing the AR antagonist proxalutamide vs placebo in outpatients with COVID-19." (PMID 35438754, 2022). "Testosterone and androgen receptor signaling may confer increased risk for SARS-CoV-2 infection and contribute to severe COVID-19 pathophysiology in men." (PMID 35602518, 2022). "Therefore, ADT when used in combination with either AR inhibitors or luteinizing hormone-releasing hormone modulators could potentially act as a propylactic therapy used as an interceptive medicine against COVID-19 patients who are suffering from a high risk of the disease." (PMID 36299504, 2022). "It predicts that a low number of CAG repeats in the AR gene correlates with high receptor activity, which, by promoting the transcription of the TMPRSS2 gene, results in an increased risk of contracting a severe form of COVID-19." (PMID 36101355, 2022). "To address a possible degradation of the AR protein due to autolysis or prolonged fixation, we also examined the presence of AR by ELISA and demonstrated the protein in the autopsy cases also with a reduction in COVID-19 cases." (PMID 35453608, 2022). "Our ERC finding indicating ACE2 and AR coevolution suggests regulatory feedback between these two proteins, which could be relevant to COVID-19 severity and other sex differential pathologies, such as cardiovascular disease." (PMID 34616619, 2021).